TSPAN5 (tetraspanin 5)
Diseases named in the same sentence as TSPAN5 in open-access papers (continued):
Sharing a sentence is not in itself a finding about the gene and the disease.
tumor (continued). "In conclusion, we have demonstrated that Tspan5 is downregulated in tumour tissue and inversely correlated with clinicopathological features and overall survival of GC patients." (PMID 27223087, 2016). "To investigate the role of Tspan5 in pathogenesis of GC in vitro, we up-regulated Tspan5 expression in tumour cells by retrovirus-mediated transduction." (PMID 27223087, 2016). "Reconstitution of either cyclin D1 or CDK4 in Tspan5-overexpressing GC cells rescues the inhibitory phenotype produced by Tspan5, suggesting that cyclin D1/CDK4 play a dominant role in mediating the suppression of tumour growth by Tspan5 in GC." (PMID 27223087, 2016). "Taken together, we conclude that Tspan5 functions as a tumour suppressor in stomach to control the tumour growth of GC." (PMID 27223087, 2016). "We reconstituted CDK4 in Tspan5-overexpressing tumour cells by transfecting the pCMV-Myc-CDK4 construct and confirmed the upregulation of CDK4 in tumour cells by Western blotting." (PMID 27223087, 2016). "Upregulation of Tspan5 expression demonstrated that Tspan5 functions as a tumour suppressor to inhibit cell proliferation in vitro and xenograft growth in vivo." (PMID 27223087, 2016). "Tspan5 was strongly expressed in adjacent tissues but weakly expressed in tumour tissues, predominantly located on membrane and in cytoplasm of the para-neoplastic cells." (PMID 27223087, 2016). "To test this hypothesis, we assessed the wound healing and Transwell migration capacity of Tspan5‐engineered tumour cells as well as the expression of EMT markers upon blockade of Notch signalling by the γ‐secretase inhibitor." (PMID 33955149, 2021). "In contrast, upon TSPAN5 knockdown the cells showed a looser and more scattered growth pattern with nests, indicating fewer tight cell–cell interactions with even partial disintegration of the tumor." (PMID 34771537, 2021). "Moreover, IHC staining on xenograft sections of metastatic foci in mouse lungs revealed that upregulation of Tspan5 in tumour cells enhanced the expression of NICD1 and nuclear localization in vivo as well." (PMID 33955149, 2021). "The analysis of the phosphorylation status of ERK1/2 and retinoblastoma protein (Rb) revealed enhanced ERK1/2 phosphorylation and hypophosphorylation of Rb in the HCC xenografts, thereby confirming the role of OIS in TSPAN5-knockdown-mediated anti-tumor effects." (PMID 34771537, 2021). "We therefore conclude that Tspan5 may regulate disease progression by increasing cell migration and tumour metastasis of HCC." (PMID 33955149, 2021). "Importantly, xenograft growth and tumor volume were strongly reduced in the TSPAN5-specific treatment group." (PMID 34771537, 2021). "Mechanistic studies revealed that Tspan5 promoted cell migration and tumour metastasis by increasing the enzymatic maturation of ADAM10 and activating Notch signalling via the increase of the cleavage of the Notch1 receptor catalysed by the γ‐secretase complex." (PMID 33955149, 2021). "Thus, our findings indicate that Tspan5 facilitates the tumour metastasis and EMT by activation of Notch signalling in HCC." (PMID 33955149, 2021). "Previously, we reported that Tspan5 is downregulated in gastric cancer tissues and functions as a tumour suppressor in stomach to control the tumour growth by regulation of cell cycle transition from G1‐S phase via decreasing the expression of cyclin D1, CDK4, pRB and E2F1." (PMID 33955149, 2021). "Tspan5 correlation analyses of TCGA tumour samples revealed that Tspan5 expression is positively correlated with the expression of ADAM10, Notch1, Notch2, Notch3, Notch4, Hey1, vimentin, N‐cadherin and Snail, whereas it is negatively correlated with E‐cadherin in HCC tissues." (PMID 33955149, 2021). "Since loss of the tumor suppressor DLC1 leads to increased HCC growth, we next investigated whether the newly identified target genes VCAN, TSPAN5 and CDH2 affect tumor characteristics such as proliferation or invasion." (PMID 34771537, 2021).
tumor (continued). "In order to test whether the regression of CAM tumors upon TSPAN5 depletion is associated with OIS, we determined OIS markers such as ERK1/2 phosphorylation in HuH7 tumor lysates." (PMID 34771537, 2021). "Thus, the results confirm that Tspan5 functions as a tumour suppressor to inhibit tumour growth of GC in vivo." (PMID 27223087, 2016). "To investigate whether Tspan5 affects tumour growth in vivo, we subcutaneously implanted Tspan5-overexpressing or control AGS cells into BALB/c nude mice." (PMID 27223087, 2016). "Upregulation of Tspan5 significantly inhibited the tumor growth in vivo." (PMID 27223087, 2016). "We demonstrated for the first time that Tspan5 is significantly upregulated in HCC and associated with tumour invasive depth, clinical stage and poor overall survival of patients, particularly those with tumour vascular invasions, heavy alcohol consumption or hepatitis virus infections." (PMID 33955149, 2021). "Thus, we hypothesized Tspan5 may be involved in tumour metastasis and disease progression of HCC patients." (PMID 33955149, 2021). "Thus, Tspan5 functions as a tumour suppressor in stomach to control the tumour growth of GC." (PMID 27223087, 2016). "Thus, the results suggest that Tspan5 may act as a tumour suppressor to control tumour growth and progression of GC in vitro." (PMID 27223087, 2016). "Thus, the results suggest that decreased expression of Tspan5 may increase tumour growth and progression while increased expression of Tspan5 is an independent favourable prognostic factor for GC." (PMID 27223087, 2016). "However, Tspan5 expression did not appear to be associated with age, gender, tumour location and differentiation." (PMID 27223087, 2016). "To investigate the role of Tspan5 in tumour metastasis of HCC, we modulated the expression of Tspan5 in HCC cells by lentivirus‐mediated transductions." (PMID 33955149, 2021). "Mechanistic studies further revealed that Tspan5 enhances the expression of active ADAM10, activates Notch signalling, promotes the epithelial–mesenchymal transition (EMT) and triggers the tumour metastasis of HCC." (PMID 33955149, 2021). "In clinical HCC samples, Tspan5 expression is strongly correlated with many key molecules acting in Notch signalling and EMT, highlighting the role of Tspan5 in the regulation of Notch signalling, EMT and tumour metastasis of HCC." (PMID 33955149, 2021). "Activation of Notch signalling by Tspan5 was shown further to enhance the epithelial–mesenchymal transition (EMT) and actin skeleton rearrangement of tumour cells." (PMID 33955149, 2021). "Alterations of Tspan5 expression by lentivirus transductions in HCC cells demonstrated that Tspan5 promotes wound healing and cell migration in vitro and tumour metastasis of HCC cells in vivo." (PMID 33955149, 2021). "IHC staining on tumour sections of metastasized lungs demonstrated that upregulation of Tspan5 significantly reduced the expression of E‐cadherin but increased the expression of vimentin in MHCC97L and BEL7402 tumours." (PMID 33955149, 2021). "In HCC clinical specimens, Tspan5 is highly correlated with the expression of all key players in Notch signalling and EMT process, highlighting the role of Tspan5 in tumour metastasis of HCC by regulation of Notch signalling and EMT." (PMID 33955149, 2021). "We investigated the pathway connection for the function that Tspan5 played in HCC metastasis, EMT and Notch signalling by blockade of Notch signalling in tumour cells with DBZ." (PMID 33955149, 2021). "We found that upregulation of Tspan5 significantly promotes the wound healing and migration of HCC cells in vitro and tumour metastasis of HCC in vivo." (PMID 33955149, 2021). "In agreement with the upregulation result, Tspan5 downregulation dramatically inhibited the wound healing and migration of HCC cells in vitro and the tumour metastasis in vivo." (PMID 33955149, 2021).
tumor (continued). "For providing the first evidence that knockdown of TSPAN5 can be used as a therapeutic approach in HCC tumor xenografts, we used a PEI-based delivery platform for TSPAN5 siRNA, thus allowing a therapeutic intervention after the establishment of the tumors." (PMID 34771537, 2021). "Nevertheless, poorly differentiated cell lines mimicked upregulated expression of genes (in tumours) such as CAV1, COL4A1, and novel candidates such as TSPAN5, TENM2, C15orf48, PLAU, AHNAK2, FAM129A, PLAU and platelet-specific phosphofructokinase (PFKP)." (PMID 30176945, 2018). "The correlation of Tspan5 expression with the expression of p27, p15, cyclin D1, CDK4, pRB and E2F1 in vivo are also revealed in xenografted tumours." (PMID 27223087, 2016). "To corroborate the role of cyclin D1 and CDK4 in the suppression of tumour growth of GC by Tspan5, we reconstituted the expression of cyclin D1 and CDK4 in Tspan5-overexpressing tumour cells." (PMID 27223087, 2016). "The more profound effects on the migration and EMT of tumour cells by DBZ than by Tspan5 itself were not surprising, as the γ‐secretase complex would act on all four Notch receptors (Notch1–4) and perhaps other proteins in HCC cells." (PMID 33955149, 2021). "Thus, the results substantiate the role of Tspan5 in the regulation of Notch signalling, EMT and tumour metastasis of HCC." (PMID 33955149, 2021). "Importantly, Tspan5 is significantly correlated with all these elements, greatly substantiating the role of Tspan5 in the regulation of Notch signalling, EMT and tumour metastasis of HCC." (PMID 33955149, 2021). "In this study, we demonstrated for the first time that the expression of Tspan5 is downregulated GC tumour tissues compared to adjacent non-tumour tissues." (PMID 27223087, 2016). "We determined the protein level of Tspan5 by immunohistochemical staining (IHC) of a cohort of 114 pairs of tumour tissues and adjacent non-tumour tissues." (PMID 27223087, 2016). "IHC staining demonstrated that upregulation of Tspan5 significantly increased the expression of p27 and p15 but dramatically decreased the expression of cyclin D1, CDK4, pRB and E2F1 in xenograft tumours compared to control tumours (all P<0.001)." (PMID 27223087, 2016). "Quantitative analysis by scoring the staining revealed that Tspan5 was significantly downregulated in tumour tissues versus in adjacent non-tumour tissues (4.51±2.61 versus 9.66±2.30, P<0.001)." (PMID 27223087, 2016). "Therefore, we speculate that specific blockades of Tspan5‐induced Notch signalling and EMT may produce significant clinical benefits for HCC patients who have had elevated activities of Tspan5, Notch signalling and EMT in their primary tumours." (PMID 33955149, 2021). "F‐actin staining of tumour cells with Rhodamine‐phalloidin revealed that upregulation of Tspan5 significantly increased the expression of F‐actin and propelled actin cytoskeleton rearrangement in both MHCC97L‐Tspan5 and BEL7402‐Tspan5 cells as compared with that of the control cells." (PMID 33955149, 2021). "We found that either cyclin D1 or CDK4 could not only reverse the inhibitory phenotype produced by Tspan5 but also promote the cell growth further as compared to the basal control, suggesting that cyclin D1/CDK4 have a dominant role in mediating the suppression of tumour growth by Tspan5 in GC." (PMID 27223087, 2016).
cancer (6 papers, 2016 to 2023). A tumor composed of atypical neoplastic, often pleomorphic cells that invade other tissues. "A genetic variant in the TSPAN5 gene with platinum-induced ototoxicity in pediatric cancer patients emerged as main candidate of interest." (PMID 36699085, 2022). "Tspan5 transcripts were significantly associated with pathological grades and individual cancer stages." (PMID 33955149, 2021). "The evaluations confirmed that TSPAN5 suppression, in turn, suppressed proliferation, migration, invasion, and tumorigenesis, which are characteristic of cancer cells." (PMID 37047447, 2023). "The findings confirmed that the HT29 cells showed lower TSPAN5 mRNA and protein expression than the other cancer cell lines." (PMID 37047447, 2023). "In a meta-analysis of all pediatric cancer cohorts (GO-CAT, United Kingdom MAGIC and PanCareLIFE), the effect of the TSPAN5 variant remained suggestively significant (OR = 1.6 (95% CI = 1.3–1.9), p = 8.9 × 10−6, I2 = 73.6%)." (PMID 36699085, 2022). "Targeting Tspan5 and/or Tspan14 has potential as an anti-Notch strategy for the treatment of Notch-driven cancers such as T-ALL and solid tumors." (PMID 34201472, 2021). "However, the function of Tspan5 in pathological processes, particularly in cancer biology and its clinical significance, are still unclear." (PMID 33955149, 2021). "We are interested in the role of Tspan5 in cancer biology and clinical significance." (PMID 27223087, 2016). "TSPAN5 has a regulatory effect on the transport of ADAM10 from vesicles to the protoplasmic reticulum, and regulatory disturbances in these interactions may be associated with disorders that cause cancer, Alzheimer’s disease, or inflammation." (PMID 37047447, 2023). "It remains to be determined whether targeting Tspan5 and/or Tspan14 will provide effective Notch inhibition for certain cancers in which these proteins are over-expressed, and whether such a treatment will have lower toxicity than existing anti-Notch strategies such as γ-sectretase inhibition." (PMID 34201472, 2021). "However, the role of Tspan5 during pathological processes, particularly in cancer biology, remains unknown." (PMID 27223087, 2016). "Notch signaling is important in promoting many cancers, so one prediction of the Tspan5/14/ADAM10 Notch activation model is that Tspan5 and Tspan14 will promote such cancers." (PMID 34201472, 2021). "TSPAN5 belongs to the TSPAN superfamily of integral membrane proteins that possess four highly conserved transmembrane proteins and organize laterally to form tetraspanin-enriched microdomains, emerging as key players in the progression of metastasis of several cancers." (PMID 34771537, 2021).
colorectal (1 paper, 2020). "Additionally, the genes that were highly expressed in colorectal patients are TSPAN2, TSPAN5, TSPAN12, TSPAN28, TSPAN29, and TSPAN33." (PMID 32694936, 2020).
digestive system cancer (1 paper, 2024). A primary or metastatic malignant neoplasm involving any part of the digestive system. "Generally, the expression of CD9, CD151, Tspan1, Tspan5, Tspan8, Tspan12, Tspan15, and Tspan31 are upregulated, facilitating the migration and invasion of digestive system cancer cells." (PMID 38389703, 2024).
TSPAN5 also shares sentences with these, for which no sentence is quoted: head and neck cancer (1 paper); kidney disease (1); osteosarcoma (1); sarcoma (1); Stroke (1).